WDR27 (WD repeat domain 27)
Synonyms: MGC43690
Tractability: No criterion of Open Targets' tractability assessment is met for any kind of drug.
Gene: Protein-coding gene on chromosome 6 (169,457,211 to 169,702,729, reverse strand). Ensembl gene ENSG00000184465.
Subcellular location (Human Protein Atlas): Nucleoplasm
Gene Ontology:
Molecular function: protein binding
Cellular component: nucleoplasm
Genetic constraint (gnomAD): Loss-of-function variants: 89 observed, 93.77 expected, observed/expected ratio (o/e) 0.95, 90% interval 0.8 to 1.13. The upper end of that interval is the gene's LOEUF score, 1.13, which puts it in group 4 of 6, group 1 being the genes least tolerant of losing a copy. Missense variants: 1,070 observed, 1,004.5 expected, observed/expected ratio (o/e) 1.07, 90% interval 1.01 to 1.12. Synonymous variants: 431 observed, 396.01 expected, observed/expected ratio (o/e) 1.09, 90% interval 1 to 1.18.
Homologues: Orthologues: chimpanzee WDR27 (99% identical), macaque WDR27 (65% identical), dog WDR27 (62% identical), mouse Wdr27 (59% identical), rat Wdr27 (59% identical), rabbit WDR27 (53% identical), guinea pig WDR27 (52% identical), pig WDR27 (52% identical), tropical clawed frog wdr27 (45% identical), zebrafish wdr27 (17% identical). Paralogues in human: TEP1 (13% identical), MAPKBP1 (12% identical), WDR62 (11% identical), NWD1 (11% identical), AHI1 (10% identical), WDR17 (9% identical), WDR7 (9% identical), POC1B (9% identical), WDR81 (9% identical), PAFAH1B1 (9% identical), POC1A (8% identical), SNRNP40 (8% identical), and 14 more.
Diseases named in the same sentence as WDR27 in open-access papers:
WDR27 is named in the same sentence as 7 diseases in open-access papers, as found by Europe PMC text mining. Sharing a sentence is not in itself a finding about the gene and the disease. The quoted sentences say what the papers report.
Alzheimer disease (2 papers, 2023 to 2025). A progressive, neurodegenerative disease characterized by loss of function and death of nerve cells in several areas of the brain leading to loss of cognitive function such as memory and language. "To further confirm an association between the UNC93A and WDR27 variants and familial genetics risk for neurologic disorders, we analyzed their presence in unrelated healthy Peruvians (n = 50) and unrelated individuals with neurological disorders (probable Alzheimer’s disease, n = 8)." (PMID 36873109, 2023). "For instance, Cluster 8 was associated with relatively lower DCDQ scores than those of other clusters but higher SCQ and RBS-R scores, with genes such as THBS2, WDR27, and ORF13F1 being associated with Alzheimer’s disease." (PMID 40440618, 2025).
type 1 diabetes (2 papers, 2019 to 2023). "Similarly, little is known about the WDR27 biological functions in the brain; however, an SNP in the intergenic region adjoining WDR27 (rs924043) was associated with type 1 diabetes, and its duplication has been seen in obese patients." (PMID 36873109, 2023). "Although the physiological function of WDR27 has not been fully demonstrated, an SNP in intergenic region adjoining WDR27 (rs924043) was associated with type 1 diabetes, which suggests that its expression may be involved in metabolic syndrome." (PMID 31170227, 2019).
metabolic syndrome (1 paper, 2019). A cluster of metabolic risk factors for CARDIOVASCULAR DISEASES and TYPE 2 DIABETES MELLITUS. "Seven genes (WDR27, GNAS, DOK7, EDN3, MCF2L, PRKG1, and CMYA5) were selected based on genomic location and relevance to metabolic syndrome." (PMID 31170227, 2019). "We investigated the correlation of DNA methylation with expression of seven genes (WDR27, GNAS, DOK7, EDN3, CMYA5, PRKG1, and MCF2L) selected on the basis of their known functions in metabolic syndrome, and their locations in functional genomic regions." (PMID 31170227, 2019).
Obesity (1 paper, 2019). Accumulation of substantial excess body fat. "In addition, duplication of WDR27 has been seen in an obese patient, which suggests that WDR27 may be overexpressed in obesity." (PMID 31170227, 2019).
post-traumatic stress disorder (1 paper, 2025). An anxiety disorder precipitated by an experience of intense fear or horror while exposed to a traumatic (especially life-threatening) event. "In addition, our findings incorporated some significant genes linked to ASD symptoms identified in previous studies, including WDR27 in Cluster 8, previously associated with sleep disturbance, and HCN1 in Cluster 19, previously associated with post-traumatic stress disorder." (PMID 40440618, 2025).
neurological disorders (1 paper, 2023). "Several studies have also found SNPs in genes located on chromosome 6q with a significant connection to neurological diseases; however, the UNC93A and WDR27 variants have not yet been associated with ADRD." (PMID 36873109, 2023).
WDR27 also shares sentences with these, for which no sentence is quoted: insomnia (2 papers).